MUC1 (mucin 1, cell surface associated)
Diseases named in the same sentence as MUC1 in open-access papers (continued):
Sharing a sentence is not in itself a finding about the gene and the disease.
colitis (30 papers, 2008 to 2025). Inflammation of the colon. "paracasei L9 on the mucus barrier in DSS-induced colitis mice, Alcian Blue (AB) staining and gene expression quantification of mucin-associated markers (Muc1, Muc2, and Tff3) were performed." (PMID 41515240, 2025). "To evaluate the efficacy of MUC1-targeted immunotherapy, we examined the preventive effect of the MUC1 DNA vaccine in an experimental colitis-associated colorectal carcinogenesis model." (PMID 36980805, 2023). "We have reported that vaccination with MUC1 DNA combined with BMDCs reduced the tumor burden in colitis-associated colorectal carcinogenesis in MUC1.Tg mice." (PMID 36980805, 2023). "In the present study, we showed that vaccination with MUC1 + BMDCs significantly reduced tumor incidence and tumor burden by inhibiting colitis-associated colorectal tumor formation." (PMID 36980805, 2023). "This study was designed to evaluate the efficacy of MUC1 DNA vaccination in the prevention of colitis-associated colorectal carcinogenesis." (PMID 36980805, 2023). "Of note, the gene expression encoding Muc1 was upgraded in DSS-induced colitis in the mouse colon and was significantly restrained by BPIS." (PMID 36479296, 2022). "In patients with UC and experimental colitis models, characterized by a thin mucin layer in association with goblet cell depletion, high expression of Muc1 and Muc4, and low expression of Muc2 and Tff3 have been reported." (PMID 33959000, 2021). "During DSS colitis, Muc2 and Muc3 expression was selectively reduced in Nr2f6-deficient colonic scrapings whereas Muc1, Muc4 and Muc5ac expression was unaltered." (PMID 28779026, 2018). "Therefore, Muc1 deficiency intensifies chronic inflammation in both Th1- and Th2-mediated colitis models." (PMID 40433382, 2025). "By using this model, we showed the development of MUC1-expressing colorectal tumors in an environment and immune system that recognizes MUC1 as a self (de novo) antigen and closely mimics the colitis-associated colorectal carcinogenesis conditions as seen in humans." (PMID 36980805, 2023). "Conversely, Muc1 KO mice have been reported to be resistant to DSS-induced colitis, possibly due to enhanced mucus barrier function or reduced T cell recruitment to the affected site." (PMID 40433382, 2025). "In DSS-induced colitis, MUC1 expression is increased and Muc1−/− mice have lower colitis severity accompanied by an increase in expression of MUC2 and MUC3 in a compensatory manner." (PMID 38612988, 2024). "MUC3A and MUC1 were selected, as MUC3A is one of the most well-understood and predominant transmembrane mucin of HT29-MTX cells and MUC1 is known to have aberrant expression in colitis-like phenotypes." (PMID 38612988, 2024). "In contrast to Muc2 and Muc3, higher Muc1 expression was detected in mice with DSS-induced colitis but was reduced by the EV treatment." (PMID 37966243, 2023). "More specifically, Muc1−/− mice were resistant to acute DSS-induced colitis, yet were more prone to gastrointestinal infection." (PMID 37174625, 2023). "MUC1 knockout mice had more severe forms of Th1- and Th2-induced colitis and increased Th17 cell-mediated responses in the colon, compared with MUC1-expressing mice." (PMID 35479093, 2022). "In MUC1-deficient mice, Th17 cells and IL-17–producing ILC3 cells were expanded and exacerbated colitis." (PMID 33178223, 2020). "As reduced Muc1 expression protects mice from DSS-induced colitis, this observation cannot be causative for the enhanced colitis sensitivity in the Nr2f6-deficient setting." (PMID 28779026, 2018). "Rectal bleeding, diarrhea and colon shortening, a macroscopic parameters of colitis severity, were more pronounced in MUC1.Tg mice compared to WT." (PMID 29285251, 2017). "It is well established that regulating Muc2 is paramount when it comes to colitis, as Muc2 deletion leads to development of spontaneous colitis in mice, which is not seen in mice deficient in other mucins, such as Muc1 or Muc13." (PMID 38397081, 2024).
colitis (continued). "Our results strongly suggest that the MUC1 vaccine is effective in preventing, although not completely, colitis-associated colorectal tumor formation when combined with purified CD11c+ BMDCs." (PMID 36980805, 2023). "Consistent with the observation that HA administration increased the number of goblet cells and expression of MUC2 in colitis mice, transplantation from HA-treated colitis mice increased the mRNA levels of Muc1 and Muc2, as well as the protein expression of MUC2." (PMID 36558542, 2022). "In addition, we observed that mice with DSS-induced colitis had decreased levels of MUC1 and MUC2 at the mRNA level." (PMID 30393231, 2018). "However, similar to our findings in murine C. rodentium infection, a reduction in MUC2 expression occurs in UC adjacent to ulceration and in active colitis, and MUC1 expression was upregulated in severe UC at the site of rupture of crypt abscesses." (PMID 19088856, 2008). "Although Muc1 was significantly increased during the course of colitis in DSS-treated mice, a compensatory increase in Muc1 expression was also seen upon acute colitis in Muc13−/− mice, which could explain the abolishment of the Muc13 knockdown effect on the barrier function upon DSS exposure." (PMID 37174625, 2023). "In knockout mice for the mucin 1 gene (Muc1−/−), the mucus layer is thicker, and they develop DSS-induced colitis of significantly less severity than in wild-type animals." (PMID 40863977, 2025). "In knockout mice for the mucin 1 gene (Muc1−/−), the mucus layer is thicker, and these animals develop DSS-induced colitis with significantly reduced severity in comparison to wild-type animals." (PMID 40863977, 2025). "Our findings demonstrate that SC-4 can colonize germ-free (GF) mice, increasing mucin thickness by activating MUC-1 and MUC-2 genes, thereby protecting GF mice from Dextran Sodium Sulfate (DSS)-induced colitis." (PMID 39069899, 2024). "Select mucins from in vivo experimental WT and AhRΔIEC colitis mice treated with or without I3C were validated in CECs, which included Muc1, Muc2, and Muc3." (PMID 38397081, 2024). "This agrees with a previous colitis study that demonstrated than the absence of Muc1 leads to the intensification of chronic inflammation and body weight loss." (PMID 34502403, 2021). "In our DSS-induced colitis model, DSS treatment yielded a slight though non-significant increase in transmembrane MUC1." (PMID 38612988, 2024).
pancreatic ductal adenocarcinoma (30 papers, 2005 to 2025). An infiltrating adenocarcinoma that arises from the epithelial cells of the pancreas. "Mucin 1 (MUC1), a transmembrane glycoprotein of mucins family, is recognized as an oncoprotein and is usually associated with invasiveness, metastasis, and resistance to therapies in pancreatic ductal adenocarcinoma." (PMID 40001578, 2025). "Mucin 1 is a transmembrane glycoprotein which overexpresses cancer-specific epitopes (MUC1-CE) on pancreatic ductal adenocarcinoma (PDAC) cells." (PMID 36230945, 2022). "If the diagnosis of pancreatic ductal adenocarcinoma is considered, ductal differentiation can be demonstrated by using additional immunohistochemical markers such as mucin-related glycoproteins (MUC1, MUC5AC) and/or oncoproteins (CEA, B72.3, CA125)." (PMID 33432559, 2021). "We evaluated the impact of MUC1 expression on outcome in a cohort of 158 patients with resected pancreatic ductal adenocarcinomas (PDAC) in the CONKO-001 study (adjuvant gemcitabine [gem] vs. observation [obs])." (PMID 34386419, 2021). "In another study, VSV-based expression of human mucin 1 (MUC1) provided significant reduction of tumor growth in mice with established pancreatic ductal adenocarcinoma xenografts." (PMID 29883422, 2018). "The MUC1 glycoprotein is overexpressed and aberrantly glycosylated in >90% of pancreatic ductal adenocarcinoma cases and impacts tumor progression by initiating downstream signaling through phosphorylation of its cytoplasmic tail." (PMID 27220889, 2016). "Mucin 1 (MUC1) is a transmembrane mucin glycoprotein that is over-expressed and aberrantly glycosylated in >80% of human pancreatic ductal adenocarcinoma (PDA) and is associated with poor prognosis." (PMID 24605110, 2014). "We used the Capan-2 pancreatic ductal adenocarcinoma (PDAC) cell line, which expresses high levels of cell-surface mucins, including MUC1, as target tumor cells." (PMID 41372740, 2025). "On the other hand, CK7, CK19, CEA, CA19-9, and MUC1 are highly sensitive for ordinary pancreatic ductal adenocarcinoma (sensitivity: 96%, 100%, 85%, 75%, and 88%, respectively), and CK7, CK19, and MUC1 were partially positive in the current tumor." (PMID 28114893, 2017). "Pancreatic ductal adenocarcinoma (PDAC) displays a typical mucin expression pattern which is characterized by MUC1 positive, MUC2 negative, and MUC5AC positive." (PMID 35910854, 2022). "Non-papillary bladder cancer, pancreatic ductal adenocarcinomas (PDAC), and stomach intestinal adenocarcinoma not otherwise specified (SIA NOS) were the only tissues that were observed to have MUC1 mutation(s) at stage II cancer." (PMID 28978023, 2017). "Additionally, it has been discovered that in pancreatic ductal adenocarcinoma (PDAC), MUC1 overexpression induces non-canonical TGF-β signaling, where MUC1 overexpression activates the JNK pathway in response to TGF-β, thus altering its function from a tumor suppressor to a tumor promoter." (PMID 38361923, 2024).
bladder cancer (29 papers, 2008 to 2025). "Different studies have reported that elevation in MUC1 expression level is directly associated with higher risk of invasion and poor prognosis in breast, colon, pancreas, and bladder cancers." (PMID 34694686, 2022). "Because MUC1 has a high diagnostic accuracy for bladder cancer, it may be a useful clinical marker and targeted treatment molecule." (PMID 38540735, 2024). "Alterations in MUC4 and MUC1 are noted in bladder cancer, pancreatic ductal adenocarcinoma, and oral squamous cell carcinoma." (PMID 40699805, 2025). "MUC1 overexpression has been found in many types of cancer, and is certainly found in bladder cancer." (PMID 38539529, 2024). "More concerning from a therapeutic side is that MUC1 proteins were found to play a significant role in bladder cancer cells acquiring resistance to cisplatin, one of the major chemotherapeutic agents used to treat bladder cancer patients." (PMID 38539529, 2024). "Although current studies have shown that MUC1 is upregulated in bladder cancer (BC), the specific mechanism is still unclear." (PMID 35879749, 2022). "Mucin 1 (MUC1) on the surface of bladder cancer cells carrying core 2 O-glycans acts as a molecular barrier to resist the attack of natural killer (NK) cells, thereby promoting bladder tumor metastasis." (PMID 32596162, 2020). "Overexpression and changes in glycosylation of MUC1 have been reported in lung, breast, ovary, colon and bladder cancer." (PMID 28248271, 2015). "Serum levels of MUC1 are elevated in patients with late stage bladder cancer but sensitivity for early disease is poor." (PMID 28248271, 2015). "Altered expression and localization pattern of MUC1 have been observed during progression of malignant neoplasms of bladder, however to date there is a dearth of information on the status of MUC4." (PMID 24671186, 2014). "It has been proposed that MUC1 has a role in bladder cancer development and treatment resistance." (PMID 38540735, 2024). "The targeted Tn-MUC1 therapy may provide higher recurrence prevention and more treatment options for higher-grade bladder cancer." (PMID 38269087, 2023). "Moreover, owing to its presence in a variety of malignant tumors (such as lung, breast, ovarian, bladder carcinomas, prostate, gastric, etc.), MUC1 has been used as an important cancer biomarker." (PMID 36431072, 2022). "The potential mechanisms of MUC1-mediated drug resistance in bladder cancer were uncovered." (PMID 35879749, 2022). "MUC1 is a glycoprotein that is overexpressed on the cell surface of most malignant epithelial cancers, including colorectal, lung, prostate, pancreatic, ovarian, and bladder cancers." (PMID 29301363, 2018). "Additionally, the pattern, intensity and depth of MUC1 immunostaining are correlated with bladder cancer grade." (PMID 29207682, 2017). "However, total MUC1 was measured whereas our data suggest that it is an alternatively glycosylated form of MUC1 that is increased in the urine of bladder cancer patients." (PMID 28248271, 2015). "This evidence supports that MUC1 can be considered as an early diagnostic biomarker (lung adenocarcinoma, pancreatic, or ovarian cancer) or as a prognostic biomarker (bladder carcinoma, node-negative breast, lung squamous cell, and esophageal cancer." (PMID 40699805, 2025). "By identifying three uEV biomarkers (mucin-1 (MUC-1), coiled-coil domain containing 25 (CCDC25), and solute carrier family 2 member 1 (GLUT1)), Pt@CP-based immunoassays are able to detect bladder cancer with high clinical specificity and sensitivity." (PMID 40072370, 2025). "Overall, mucin MUC1 and MUC4 analyses in bladder cancer TMA and tissue sections indicated that the expression of MUC1 is increased while that of MUC4 decreased in UC compared to the normal non-neoplastic urothelium." (PMID 24671186, 2014).
bladder cancer (continued). "The present study examined the expression of TM mucins MUC1 and MUC4 in bladder tissue microarray, tissue sections and bladder carcinoma cell lines." (PMID 24671186, 2014). "Our findings indicate that the more invasive bladder cancer cells interact thanks to one or two types of ICAM-1 ligands: CD43 and MUC1 are good candidates, as demonstrated by flow cytometry experiments." (PMID 24857933, 2014). "After analyzing the expression of mucins in various bladder pathologies by immunohistochemistry, the expression of MUC1 and MUC4 was analyzed at mRNA and protein levels in different bladder carcinoma cell lines." (PMID 24671186, 2014). "Additionally, NRAS, EHD4, ITGB1 and MUC1, which were among the protein set correlating with bladder cancer on PCA, have been found in various studies of bladder cancer exosomes." (PMID 32249794, 2020). "Recently, the use of improved AdnaTest immune-magnetic systems also allowed the identification of CTC with stem-like features by PCR-based methods, showing that ALDH1 mainly contributed to CTC positivity compared to EPCAM, MUC1, or ERBB2 in bladder cancer patients." (PMID 28321147, 2017). "Additionally, there are the TACAs which are found in bladder cancer tissues but not normal tissues, as well as glycan heavy molecules such as MUC1 whose levels correlate strongly with bladder cancer presence and progression." (PMID 38539529, 2024). "In the present study, we investigated the expression profile of MUC1 and MUC4 in the non-neoplastic bladder urothelium, in various malignant neoplasms of bladder and in bladder carcinoma cell lines." (PMID 24671186, 2014). "Concerning the molecular structure linking cancer cells to the endothelium, since bladder cancer cells do not express common ICAM-1 ligands, such as LFA-1 or Mac-1, possible ligands on the cancer cell could very well be the MUC1 or CD43 ligands." (PMID 24857933, 2014). "No expression of MUC1 and MUC4 was observed in T24 bladder carcinoma cell line." (PMID 24671186, 2014).
sarcoidosis (29 papers, 2005 to 2025). Sarcoidosis is a multisystemic disorder of unknown cause characterized by the formation of immune granulomas in involved organs. "Recent studies have been published proposing new potentially more specific and sensitive biomarkers for sarcoidosis such as soluble interleukin-2 receptor (sIL-2R) or the elevation of Krebs von den Lungen-6 (KL-6), a human MUC1 mucin protein." (PMID 33805490, 2021). "This study has shown that the molecular structural variants of KL-6/MUC1 and its leakage behavior affect changes in serum levels of KL-6 in sarcoidosis." (PMID 22650152, 2012). "The molecular structural variants of KL-6/MUC1 and its leakage behavior affect serum levels of KL-6 in sarcoidosis." (PMID 22650152, 2012). "In addition, serum KL-6 levels have been reported to be influenced by the molecular size of MUC1 in healthy controls or in patients with sarcoidosis." (PMID 28403862, 2017). "Considering for the molecular size of KL-6/MUC1 and its leakage behavior may increase the value of serum KL-6 as a marker of sarcoidosis." (PMID 22650152, 2012).
hypersensitivity pneumonitis (26 papers, 2005 to 2025). Hypersensitivity pneumonitis (HP) is a pulmonary disease with symptoms of dyspnea and cough resulting from the inhalation of an antigen to which the subject has been previously sensitized. "Our results suggest that high molecular size KL-6/MUC1 might transfer from the alveoli to blood circulation as a result of alveolitis." (PMID 22650152, 2012). "SP-D and KL-6/MUC1 are useful biomarkers in the diagnosis of various ILDs, such as IPF, collagen vascular disease-associated interstitial pneumonitis, radiation pneumonitis, hypersensitivity pneumonitis, pulmonary alveolar proteinosis, and drug-induced pneumonitis." (PMID 21637370, 2011).